ITIH2 (inter-alpha-trypsin inhibitor heavy chain 2)
Diseases named in the same sentence as ITIH2 in open-access papers (continued):
Sharing a sentence is not in itself a finding about the gene and the disease.
fibrosis (1 paper, 2023). the formation of excess fibrous connective tissue in an organ or tissue in a reparative or reactive process. "The results cited above have indicated that IaI shows higher levels in patients with fibrosis; however, the expression of the lung ITIH2 gene decreases." (PMID 38203636, 2023).
glioblastoma multiforme (1 paper, 2024). "ITIH2 is expressed in low-grade CNS cancers and normal brain tissues; however, it is not expressed in glioblastomas, especially glioblastoma multiforme, which is a highly invasive CNS tumor." (PMID 39149600, 2024).
hepatocellular carcinoma (1 paper, 2025). A malignant tumor that arises from hepatocytes. "ITIH2 mRNA is downregulated in multiple solid tumors, while ITIH1 mRNA undergoes downregulation in hepatocellular carcinoma." (PMID 40178908, 2025).
kidney tumors (1 paper, 2022). "Loss or downregulation of ITIH2 expression was observed in 70%, 71%, and 70% of breast, lung, and kidney tumors, respectively." (PMID 36233212, 2022).
liver cancer (1 paper, 2021). An epithelial or non-epithelial malignant neoplasm that arises from the liver. "According to the Human Protein Atlas, ITIH2 is enriched in normal liver tissues and liver cancer tissues." (PMID 34907282, 2021).
metabolic syndrome (1 paper, 2016). A cluster of metabolic risk factors for CARDIOVASCULAR DISEASES and TYPE 2 DIABETES MELLITUS. "In the present study, increased abundance of ITIH2 was observed in obese dogs with ORMD and, to the authors’ knowledge, no previous studies have linked this protein to metabolic syndrome." (PMID 27646300, 2016).
metastatic tumors (1 paper, 2025). "In the same database, ITIH2 expression was higher in lung metastatic tumors compared with primary tumors." (PMID 40178908, 2025).
Shock (1 paper, 2025). The state in which profound and widespread reduction of effective tissue perfusion leads first to reversible, and then if prolonged, to irreversible cellular injury. "Our study supports the findings regarding ITIH2 and ITIH3, but we observed a significant decrease in ITIH1 plasma levels in patients with septic shock while AMBP remained unchanged." (PMID 40885913, 2025).
thyrotoxicosis (1 paper, 2022). A hypermetabolic syndrome caused by the elevation of thyroid hormone levels in the serum. "In the present study, Itih1, Itih2, Itih3, and Itih4 were downregulated in thyrotoxicosis mice, which also reflected the decline of defense and protective capability." (PMID 35720307, 2022).
tuberculosis (1 paper, 2024). A chronic, recurrent infection caused by the bacterium Mycobacterium tuberculosis. "ITIH2 was also proposed as a potential biomarker of tuberculosis and was considered as a tumor growth inhibitor when overexpressed." (PMID 38792644, 2024).
tumor (26 papers, 2008 to 2026). "As a secreted protein, ITIH2 is expected to be present in both normal and tumor tissue, as well as in various locations, including plasma within vessels and in the extracellular medium." (PMID 40005870, 2025). "In primary tumors, both ZEB1 and ITIH2 were highly expressed at the invasive front of the tumor edge compared with the central region, indicating that they promote invasive potential." (PMID 40178908, 2025). "Further studies are needed to understand better the specific roles of ITIH2 and the HA matrix at each metastasis stage, including primary tumor dissemination, lymph node invasion, circulation, and colonization." (PMID 40178908, 2025). "Supporting our findings, they observed a similar trend where ITIH2 expression decreased in tumor tissues, with distinct differences between adjacent normal tissue, LRPCa, and HRPCa samples." (PMID 40136513, 2025). "They observed significant changes in the levels of inter-alpha-trypsin inhibitor heavy chains (such as ITIH2) due to their implication in tumor growth and the malignancy process." (PMID 39061201, 2024). "ITIH2 plays important roles in extracellular matrix stabilization and in the prevention of tumor metastasis." (PMID 35898512, 2022). "ITIH2 codes for the inter-alpha-trypsin inhibitor heavy chain H2, a protein from a family of structurally related plasma serine protease inhibitors playing a key role in extra-cellular matrix biology and tumor progression." (PMID 33836786, 2021). "Altogether, the close association between ITIH2 and ITIH5, and their strong correlation with the estrogen receptor status, suggest that these molecules interact in their tumor-suppressive and metastasis-repressive properties." (PMID 18226209, 2008). "For a further analysis of ITIH expression on the protein level, we selected ITIH2 expression in normal and malignant breast tissue, since out of all ITIH family members, ITIH2 showed the most frequent downregulation (70%) in this tumor entity." (PMID 18226209, 2008). "ITIH2 appears to have a dual, context-dependent function in tumor biology." (PMID 40005870, 2025). "Because ITIH2 has an estrogen-binding structural domain that profoundly affects ECM integrity and may therefore be crucial for tumor growth and metastasis, there used to be a high correlation between ITIH2 expression levels and estrogen levels." (PMID 39149600, 2024). "The protein encoded by ITIH2 belongs to the inter-alpha-trypsin inhibitor (ITI) family, members of which are structurally related plasma serine protease inhibitors involved in the stabilization of the extracellular matrix and in the prevention of tumor metastasis." (PMID 32571425, 2020). "However, looking at expression patterns of the different heavy chain genes, there may be redundancy in their tumor suppressive functions, as e.g. ITIH2 and ITIH5 are both abundantly expressed in normal breast tissue." (PMID 18226209, 2008). "Analysis of differential expression between GC tumor tissues and normal tissues revealed upregulated SERPINE1, IL1F10, IGFBP1, and ITIH2, whereas C6, GCG, GRP, and APOD were downregulated." (PMID 41551463, 2026). "This study investigated the expression of two potential biomarkers—Inter-Alpha-Trypsin Inhibitor Heavy Chain 2 (ITIH2) and Enolase 1 (ENO1)—in the mammary glands of healthy and tumor-bearing dogs using immunohistochemistry." (PMID 40005870, 2025). "Inter-alpha-trypsin inhibitor heavy chain 2 (ITIH2), a constituent of the ITI protein family, plays a crucial role in stabilizing the extracellular matrix and impeding tumor metastasis." (PMID 39355132, 2024).
tumor (continued). "Remarkably, hepatocyte areas adjacent to dHGP CRCLM showed upregulation of genes involved in tumor suppression and metastasis inhibition such as G0S2, ITIH2 and DCN." (PMID 36691028, 2023). "We also observed that the expression levels of ITIH1, ITIH3, and ITIH4 increased with tumor staging of KIRC patients, as did that of ITIH2 in KIRP patients." (PMID 33744857, 2021). "Significant alterations in Inter-alpha-trypsin inhibitor heavy chains (ITIH1, ITIH2, ITIH3, and ITIH4) levels were also observed due to their implication in tumor growth and the malignancy process." (PMID 32023884, 2020). "ITIH2 was shown to be down-regulated in tumours of the breast, compared with other ITIH proteins, suggesting its potential function as tumour suppressor or metastasis repressor." (PMID 27646300, 2016). "The results showed specific patterns of expression for both ITIH2 and ENO1, suggesting that these proteins may play important roles in tumor development." (PMID 40005870, 2025). "ITIH2, known for its involvement in stabilizing the ECM, may reflect critical adaptations within the tumour microenvironment, potentially facilitating structural changes conducive to tumour growth and metastasis." (PMID 39641316, 2024). "In case of abundant expression, ITIH2 was homogeneously distributed across the tumor masses and showed neither a patchy expression pattern, nor a particular concentration at the tumor invasion front (data not shown)." (PMID 18226209, 2008). "Additionally, TIMER analysis indicated that ITIH2 expression is correlated with immune cell infiltration, specifically with B cells, CD4+ T cells, CD8+ T cells, macrophages, neutrophils, and dendritic cells, suggesting a potential role for ITIH2 in the tumor microenvironment and immune response." (PMID 40136513, 2025). "Although the expression levels of ITIH2, ITIH3, and ITIH4 also differed in different tumor stages of LIHC, the expression change directions were not always identical." (PMID 33744857, 2021).
cancer (12 papers, 2009 to 2025). A tumor composed of atypical neoplastic, often pleomorphic cells that invade other tissues. "In conclusion, ZEB1 orchestrates cancer cell migration and invasion through comprehensive regulation of the HA network, including ITIH2." (PMID 40178908, 2025). "A comprehensive understanding of ITIH2’s role in tumors requires considering the specific cancer type, disease stage, and the surrounding microenvironment." (PMID 40005870, 2025). "Given the pivotal role of ITIH2 in cancer cell invasion and metastasis, directing therapeutic interventions toward ITIH2 poses a promising strategy." (PMID 40178908, 2025). "By focusing on ITIH2, this approach allows finer control over the cellular microenvironment, offering a potentially more efficient therapeutic strategy for cancer." (PMID 40178908, 2025). "Through transcriptome and secretome analyses, we identified ITIH2 as a key regulator of CAF motility in mesenchymal-like cancer cells." (PMID 40178908, 2025). "Moreover, our findings indicate that sincalide, a specific ITIH2 inhibitor identified through deep learning–based screening, has the potential to disrupt the HA matrix, thereby preventing cancer progression." (PMID 40178908, 2025). "Similarly, Inter-alpha-trypsin inhibitor heavy chain H2 (ITIH2) has recently been implicated in motility and invasiveness of cancer cells via the hyaluronan network." (PMID 41302034, 2025). "Nevertheless, the precise mechanism through which ITIH2 operates in cancer remains ambiguous." (PMID 39355132, 2024). "Numerous investigations have substantiated ITIH2 as a significant molecular indicator for cancer." (PMID 39355132, 2024). "These actions may stem from the influence of vitamin D on the expression of genes associated with collagen production, such as SHMT1, UGT1A6, and ITIH2.The anti-cancer properties of vitamin D are also supported by changes in KLHL3 and TTPA gene expression." (PMID 38203636, 2023). "In this study, we demonstrated that ZEB1 controls ITIH2 and other components involved in the reconstruction of the HA matrix, propelling changes in the lung TME that enhance cancer cell migration and invasion." (PMID 40178908, 2025). "This study investigated the immunohistochemical expression of ITIH2 and ENO1 in mammary tissues from healthy dogs and those with benign and malignant tumors." (PMID 40005870, 2025). "This analysis highlights distinct expression patterns for ITIH2 and RCN1, suggesting their potential roles as biomarkers across various cancers." (PMID 40136513, 2025). "Hyaluronic acid cross-linking with ITIH2 via tumor necrosis factor-induced protein 6 (TSG6) reduces its degradation and alters extracellular matrix (ECM) interactions, which may offer cancer-protective effects." (PMID 40005870, 2025).
infection (5 papers, 2019 to 2022). The state of being infected such as from the introduction of a foreign agent such as serum, vaccine, antigenic substance or organism. "Only three proteins, Itih2, A1bg, and Kng2, were significantly increased during infection with the WT strain only." (PMID 34721327, 2021). "In this study, ITIH1, ITIH2, were found to be negative acute phase reactants while ITIH3, and ITIH4 acted as positive acute phase proteins during both infection types in NHPs." (PMID 30774579, 2019).
bacterial infection (1 paper, 2025). "Patients with bacterial infection had lower plasma levels of AMBP and ITIH2, an increase in ITIH3, while ITIH1 remained unchanged compared with healthy controls." (PMID 40885913, 2025).
malignant carcinoma (1 paper, 2024). "The literature describes that ITIH2 may present significant downregulation in solid tumors, contrary to the results obtained in the study by Kopylov and colleagues (2020) and in our study, which observed a greater abundance of the ITIH2 protein in the malignant carcinoma group." (PMID 39061201, 2024).
ITIH2 also shares sentences with these, for which no sentence is quoted: invasive carcinoma (2 papers); nervous system diseases (2); brain tumors (1); cervical squamous cell carcinoma (1); CNS tumors (1); demyelinating disease (1); Insulin resistance (1); kidney disease (1); melanoma (1); metabolic disease (1); multiple sclerosis (1); ovarian carcinoma (1); ovarian serous cystadenocarcinoma (1); pancreatic cancer (1); prostate carcinoma (1); thyroid carcinoma (1); trichinellosis (1).